FSTL3 (follistatin like 3)
Diseases named in the same sentence as FSTL3 in open-access papers (continued):
Sharing a sentence is not in itself a finding about the gene and the disease.
lung adenocarcinoma (3 papers, 2022 to 2025). A carcinoma that arises from the lung and is characterized by the presence of malignant glandular epithelial cells. "FSTL3 is significantly associated with the prognosis and progression of lung adenocarcinoma and the infiltration of immune cells." (PMID 38240936, 2024). "We investigated the association between FSTL3 expression and clinical characteristics and immune cell infiltration in lung adenocarcinoma samples from The Cancer Genome Atlas (TCGA) and a separate validation set from our hospital." (PMID 38240936, 2024). "Considering the association of FSTL3 with diverse immune cell infiltrates, we intend to assess the therapeutic efficacy of immunotherapy strategies that target FSTL3 in treating lung adenocarcinoma." (PMID 38240936, 2024). "Thus, targeting FSTL3 and its associated genes in immunotherapy could be potentially beneficial for the treatment of lung adenocarcinoma." (PMID 38240936, 2024). "Our investigation revealed a notable diminution in FSTL3 expression among lung adenocarcinoma patients, which exhibited a significant correlation with N stage, pathological stage, and overall survival metrics." (PMID 38240936, 2024). "We plan to investigate the impact of FSTL3 downregulation or overexpression on tumor growth, metastasis, and immune evasion in lung adenocarcinoma." (PMID 38240936, 2024). "Looking forward, we aim to implement animal model experiments to substantiate the function and mechanisms of FSTL3 in lung adenocarcinoma more robustly." (PMID 38240936, 2024). "FSTL3 expression was markedly reduced in patients with lung adenocarcinoma." (PMID 38240936, 2024). "However, the role and mechanism of action of FSTL3 in lung adenocarcinoma development and tumor immunity are unknown." (PMID 38240936, 2024). "The prognosis of patients with lung adenocarcinoma was significantly affected by six genes (KRT6A, VEGFC, KRT14, KRT17, SNORA12, and KRT81) related to FSTL3." (PMID 38240936, 2024). "Concurrently, we will delve into the interactions between FSTL3 and other pertinent genes, such as KRT6A, VEGFC, KRT14, KRT17, SNORA12, and KRT81, to enhance our understanding of its role in lung adenocarcinoma progression and to pinpoint novel therapeutic targets." (PMID 38240936, 2024).
thyroid cancer (3 papers, 2021 to 2022). "Subsequently, molecular experiments, cell experiments and animal model experiments confirmed that lncRNA LBX2-AS1 can recruit the TF RARα to foster the expression of FSTL3 to boost development of thyroid cancer." (PMID 34858481, 2021). "Here, FSTL3 was prominently highly expressed in thyroid cancer tissue through bioinformatics analysis." (PMID 34858481, 2021). "The rescue experiments showed that LBX2-AS1 recruited the TF RARα to hasten the transcription activity of FSTL3 and thus promoted the development of thyroid cancer." (PMID 34858481, 2021). "In vivo experiments in nude mice confirmed our conjecture, indicating that LBX2-AS1 modulated the expression of FSTL3 by recruiting RARα to accelerate the progression of thyroid cancer." (PMID 34858481, 2021). "Subsequently, through cell experiments, molecular experiments, and in vivo experiments, it was unveiled that LBX2-AS1 boosts the transcriptional activity of FSTL3 by recruiting the binding of RARα, thereby hastening progression of thyroid cancer cells." (PMID 34858481, 2021). "Combining a previous study, it was believed that lncRNA LBX2-AS1 regulates the progression of thyroid cancer through FSTL3." (PMID 34858481, 2021). "LBX2-AS1 upregulates the expression of FSTL3 by recruiting RARα to the FSTL3 promoter, which suggests that FSTL3 may play a role in accelerating the progression of thyroid cancer." (PMID 36325361, 2022). "In this study, combined with the bioinformatics analysis and research of predecessors, it was speculated that LBX2-AS1 modulated the expression of FSTL3 by recruiting RARα to hasten the progression of thyroid cancer." (PMID 34858481, 2021). "Our study revealed that the lncRNA LBX2-AS1/RARα/FSTL3 axis may affect the progression of thyroid cancer through bioinformatics method." (PMID 34858481, 2021). "In addition, it was further confirmed by rescue experiments that LBX2-AS1 regulated progression of thyroid cancer cells through FSTL3." (PMID 34858481, 2021). "Collectively, this study uncovered the LBX2-AS1/RARα/FSTL3 modulatory axis in thyroid cancer." (PMID 34858481, 2021). "Combining the previous research and bioinformatics research results, this study speculated that the lncRNA LBX2-AS1/RARα/FSTL3 axis can affect the development and progression of thyroid cancer." (PMID 34858481, 2021).
breast fibroadenoma (2 papers, 2009 to 2017). "This dissociation has been documented in breast fibroadenoma that overexpressed follistatin but not FSTL3." (PMID 28178680, 2017).
colon cancer (2 papers, 2021 to 2025). "To explore the roles of FABP4, CDR2L, and FSTL3 in cellular composition and molecular profiles, we analyzed single-cell RNA-sequencing (scRNA-seq) data from 49,589 cells derived from 23 colon cancer samples (GSE200997)." (PMID 40595026, 2025). "In conclusion, FABP4, CDR2L, and FSTL3 can be used as prognostic markers for colon cancer." (PMID 40595026, 2025). "Here we report that the expression level of FSTL3 in colon cancer specimens was significantly higher, compared to normal tissue and interestingly, the expression of FSTL3 was related to lymph node metastasis, tumor stage, tumor size, and intravascular emboli (IVE)." (PMID 34395416, 2021).
COVID-19 (2 papers, 2022 to 2024). A disease caused by infection with severe acute respiratory syndrome coronavirus 2. "FSTL3 has been implicated as a marker of COVID-19—CVD complications; however, no SNPs were found to be significantly correlated with hospitalisation for LGALS9, LAMP3, PRSS8 or AGRN." (PMID 39334929, 2024).
fibrosis (2 papers, 2022 to 2023). the formation of excess fibrous connective tissue in an organ or tissue in a reparative or reactive process. "FSTL3 expression was enriched in the liver of NAFLD patients with significant and advanced fibrosis, and serum FSTL3 partially mediated the association of increased liver fibrosis risk with AMI in T2DM patients." (PMID 37904173, 2023). "There were 323 individuals (191 without AMI and 132 with AMI) in T2DM co-existent NAFLD patients who had serum samples, and serum FSTL3 was tested and mediation effect of FSTL3 in association of NAFLD fibrosis and AMI was performed." (PMID 37904173, 2023). "Most importantly, analysis of the level of mediation revealed that increased serum FSTL3 partially mediated the association of increased NAFLD fibrosis risk with AMI in T2DM patients with co-existent NAFLD." (PMID 37904173, 2023). "Likewise, serum FSTL3 level was much higher in NAFLD fibrosis high risk patients than in those with NAFLD fibrosis low and intermediate risk, both by NFS and FIB-4." (PMID 37904173, 2023). "Both significant and advanced NAFLD fibrosis patients had far more FSTL3-positive area shown by AOD [0.37 (0.32, 0.41) vs 0.09 (0.07, 0.15), p < 0.001] than patients with F0 and F1 fibrosis." (PMID 37904173, 2023). "Then, GEO database analysis and immunohistochemical staining demonstrated overexpression of hepatic FSTL3 as NAFLD fibrosis progressed." (PMID 37904173, 2023). "Serum FSTL3 partially mediated the association of increased FIB-4 fibrosis risk with AMI in NAFLD and T2DM patients without adjusting for other factors, and explained 21.92% of the association." (PMID 37904173, 2023). "In addition, analysis of Gene Expression Omnibus (GEO) database and immunohistochemical staining confirmed the increased expression of FSTL3 in the liver of NAFLD patients with fibrosis." (PMID 37904173, 2023). "Immunohistochemical staining of FSTL3 was also performed on liver biopsy specimens from 30 NAFLD patients with significant and advanced fibrosis (F2 and F3) and 30 NAFLD patients with fibrosis stage F0 and F1." (PMID 37904173, 2023). "Our study show that activated FAP-derived Fst and Fstl3 might block TGF-β and myostatin signaling, thereby promoting fast recovery of muscle in a fibrosis-free healthy way." (PMID 36411280, 2022).
glioblastoma multiforme (2 papers, 2022). "FSTL3 is also involved in the dysregulation of other cancer stem cells; for example, FSTL3 facilitates the proliferation, invasion, and drug resistance of glioblastoma multiforme stem cells." (PMID 36325361, 2022).
hepatocellular carcinoma (2 papers, 2024). A malignant tumor that arises from hepatocytes. "The expression of FSTL3 in hepatocellular carcinoma tissues is lower than that in normal liver tissues." (PMID 38240936, 2024).
liver fibrosis (2 papers, 2023 to 2025). "Lastly, the mediating effect of serum follistatin-like protein 3 (FSTL3) is found to be associated with increased liver fibrosis risk in patients with MI and T2D (n = 1,424), using the Gene Expression Omnibus (GEO) analysis." (PMID 40264510, 2025). "Most importantly, we found that serum FSTL3 partially mediated the association of increased liver fibrosis risk with AMI in T2DM patients." (PMID 37904173, 2023). "Simply described, liver fibrosis will increase serum FSTL3, and FSTL3 will reach the coronary artery through the circulation and affect the prevalence and development of AMI." (PMID 37904173, 2023). "It is possible that elevated circulating FSTL3 derived from the liver of patients with hepatic fibrosis mediates the pro-atherogenic effect in T2DM." (PMID 37904173, 2023).
melanoma (2 papers, 2021 to 2024). A malignant, usually aggressive tumor composed of atypical, neoplastic melanocytes. "Because nuclear translocation of YAP1 is modulated by the Wnt/β-Catenin pathway in melanoma-associated fibroblasts and YAP1 is necessary to transactivate FSTL3 gene expression, we hypothesized that elevated FSTL3 expression modulates β-Catenin signaling in CRC." (PMID 34395416, 2021). "We also found that although some established YAP/TAZ target genes (CRIM1, F3, ANKRD1) correlated strongly with CTGF and CYR61 expression in human melanoma, others did not (WWC1, FOSL1, FSTL3)." (PMID 38473214, 2024).
renal cell carcinoma (2 papers, 2021 to 2022). "High FSTL3 expression is associated with high malignancy in colorectal, gastric, thyroid, NSCLC, and renal cell carcinoma, which suggest that FSTL3 may be a promising target in the clinical treatment of malignant tumors." (PMID 36325361, 2022).
bladder cancer (1 paper, 2025). "The PD-1/PD-L1 immunotherapy based on bladder cancer further demonstrated that high levels of FABP4, CDR2L, and FSTL3 expression were associated with a poor response to immunotherapy, confirming the applicability of the associated immune dysregulation across various tissues and diseases." (PMID 40595026, 2025).
clear renal cell carcinoma (1 paper, 2021). "The biological information analysis revealed that FSTL3 expression in clear renal cell carcinoma (KIRC) was notably higher than that in normal tissues adjoining cancer." (PMID 34555811, 2021).
coronary atherosclerosis (1 paper, 2023). Atherosclerosis of the coronary vasculature. "Previous studies have partially clarified the possible relationship between FSTL3 and coronary atherosclerosis and AMI." (PMID 37904173, 2023). "In addition, peripheral FSTL3 level and cardiac FSTL3 level have been found to be related to coronary atherosclerosis and AMI, respectively." (PMID 37904173, 2023).
ischemia (1 paper, 2023). A hypoperfusion of the BLOOD through an organ or tissue caused by a PATHOLOGIC CONSTRICTION or obstruction of its BLOOD VESSELS, or an absence of BLOOD CIRCULATION. "For example, it has been shown that the expression of Fstl3 is up-regulated in the heart of an AMI animal model, and induction of FSTL3 inhibits the cardioprotective effect of activin A, thus increasing sensitivity of the myocardium to ischemia." (PMID 37904173, 2023).
ischemic disease (1 paper, 2018). Lack of blood supply to an area of the body, resulting in impairment of tissue oxygenation. "Indeed, the findings of the present study demonstrate an important role of FSTL3 in iPS‐ECs, and in the early stages of EC differentiation, which may be significant toward our aim of generating therapeutically relevant ECs for use in both regenerative medicine and treatment of ischemic diseases." (PMID 29569797, 2018).
lung squamous cell carcinoma (1 paper, 2023). "The risk score of patients with lung squamous cell carcinoma = 0.2380 * FSTL3 + (-0.1532) * RGMA." (PMID 37308925, 2023).
nonalcoholic fatty liver disease (1 paper, 2022). "FSTL3 levels are increased in patients with nonalcoholic fatty liver disease (NAFLD), with higher FSTL3 levels correlating with increased disease severity." (PMID 36325361, 2022).
ovarian carcinoma (1 paper, 2025). A malignant neoplasm originating from the surface ovarian epithelium. "We measured levels of follistatin (FST) and follistatin-like 3 (FSTL3) in 96 ovarian cancer patient ascites samples and found that FSTL3 overexpression was more predominant than FST and associated with poorer survival outcomes." (PMID 41029436, 2025). "We next sought to evaluate if FSTL3 overexpression was associated with a particular ovarian cancer molecular histotype." (PMID 41029436, 2025). "• High FSTL3 levels in patient ascites fluid is associated with poor outcomes in ovarian cancer." (PMID 41029436, 2025). "The identification of FST as a potential player in immune evasion and treatment resistance has paved the way for exploring the role of other follistatin homologs such as FSTL3 in ovarian cancer." (PMID 41029436, 2025). "We investigated the role of FSTL3 in ovarian cancer progression both as a prognostic biomarker and as a potential therapeutic target." (PMID 41029436, 2025). "In our syngeneic ovarian cancer model, FSTL3 overexpression significantly altered the tumor immunocyte composition, by reducing total CD45+ infiltration, and specifically NK cells, B cells, T cells, macrophages, and dendritic cells." (PMID 41029436, 2025). "• Overexpression of Fstl3 in a syngeneic mouse ovarian cancer model promotes a fibrotic tumor microenvironment and immunocyte exclusion." (PMID 41029436, 2025). "In this study, we identified significant overexpression of both FST and FSTL3 in 96 ascites samples from ovarian cancer patients." (PMID 41029436, 2025). "Experimental overexpression of FSTL3 in murine ovarian cancer cells changed the TME by promoting cancer cell EMT, increasing stromal fibrosis, reducing immunocyte recruitment, and promoting T cell exhaustion, which we speculate contributed to the induced resistance to PPC combination immunotherapy." (PMID 41029436, 2025). "To evaluate the relative expression of FST and FSTL3 in ovarian cancer, we measured the concentrations of these proteins by ELISA in 96 ascites samples from 77 patients with various peritoneal tumors of ovarian cancer and other origins, both chemo-naïve and treated." (PMID 41029436, 2025). "Thus, FSTL3 may represent both a new secreted biomarker to optimize patient stratification, monitor disease burden and treatment response, and a potential target to overcome resistance to immune checkpoint therapies in ovarian cancer." (PMID 41029436, 2025). "However, the precise mechanism leading to these changes, and particularly the ligands modulated by FSTL3 in the context of the TME that directly regulate immunocytes, remain to be identified in ovarian cancer." (PMID 41029436, 2025).
ovarian tumors (1 paper, 2025). "In summary, our data suggest that ovarian tumors secrete FSTL3 in the blood and ascites and that it is an indicator of poor prognosis." (PMID 41029436, 2025). "This study aimed to understand how FSTL3 contributes to ovarian tumor development and aggressiveness, and if it regulates the tumor immune microenvironment." (PMID 41029436, 2025). "Next, we aimed to investigate the expression levels of FST and FSTL3 in human ovarian tumor tissues." (PMID 41029436, 2025). "Importantly, we found that FSTL3 could also be detected in the serum of mice bearing ovarian tumors, and observed a strong relationship between FSTL3 concentration and tumor growth." (PMID 41029436, 2025). "To better understand the consequence of FSTL3 overexpression on ovarian tumor growth and response to therapy, we used the parental cell line KPCA.FSTKO to generate a cell line overexpressing human FSTL3 (KPCA.FSTKO_hFSTL3)." (PMID 41029436, 2025).
prostate carcinoma (1 paper, 2021). A carcinoma that arises from epithelial cells of the prostate gland. "Pharmacological inhibition of YAP1 nuclear translocation drastically reduced FSTL3 expression and a positive correlation between YAP1 and FSTL3 mRNA expression was very recently shown in prostate cancer." (PMID 34395416, 2021).
rectal adenocarcinoma (1 paper, 2024). "Additionally, we found that FSTL3 expression levels were negatively correlated with CD8+ T cell infiltration levels and positively correlated with Tregs infiltration levels in colon and rectal adenocarcinoma tissues." (PMID 38302412, 2024).
systemic sclerosis (1 paper, 2018). A chronic disorder, possibly autoimmune, marked by excessive production of collagen which results in hardening and thickening of body tissues. "MDK and FSTL3 were also examined in other clinical subgroups of systemic sclerosis and were shown to be specifically upregulated compared to dcSSc, lcSSc-ILD (diagnosed by HRCT), healthy controls were included for reference." (PMID 30115106, 2018).